MTA1 (metastasis associated 1)
Diseases named in the same sentence as MTA1 in open-access papers (continued):
Sharing a sentence is not in itself a finding about the gene and the disease.
prostate carcinoma (continued). "Because of our long-standing interest in targeting MTA1 signaling, we asked whether GPE acts through inhibition of MTA1 oncogenic protein in prostate cancer, as we have shown for Res and Pter, which has significant MTA1-mediated anticancer effects." (PMID 30463302, 2018). "The findings of the direct link between MTA1 and pro-lymphangiogenic VEGF-C, which promotes tumor metastasis to distant organs, one more time emphasizes the importance of MTA1 in the promotion of prostate cancer metastasis to distant organs such as bone." (PMID 26943043, 2016). "Interestingly, in a mouse model of prostate cancer driven by PI3K-AKT-mTOR hyperactivity, elevated protein levels of YB-1 and MTA1 were observed early in disease pathogenesis within PIN lesions prior to the development of invasion and metastasis." (PMID 25797255, 2015). "The work presented in this study suggests that the regulation of E-cadherin by MTA1 may be an important step for cellular transformation, and p-AKT serves as the mediator for this regulation in prostate cancer cells." (PMID 23227138, 2012). "MTA1 antigen reacted with 2 of 13 allogeneic prostate cancer patient sera tested, but no sera reactivity was observed to any of the normal adult sera tested." (PMID 18949081, 2008). "The expression pattern of MTA1 transcripts in a panel of normal human tissues, matched human non-tumour and tumour tissues, human prostate cancer tissues and cell lines was analysed by RT-PCR." (PMID 18949081, 2008). "We and others previously identified Y-box binding protein 1 (YB-1) and metastasis associated-1 (MTA1) as proteins regulated at the translation, and not mRNA transcription level downstream of the PI3K-AKT-mTOR signaling pathway, which is frequently deregulated in human prostate cancer." (PMID 25797255, 2015). "Given that YB-1 and MTA1 are translationally regulated mRNAs, we hypothesized that differences could be observed at the protein level between normal, pre-invasive prostatic intraepithelial neoplasia (PIN), and prostate cancer tissues despite the lack of alterations at the DNA and mRNA levels." (PMID 25797255, 2015).
hepatocellular carcinoma (19 papers, 2012 to 2026). A malignant tumor that arises from hepatocytes. "TRIM25 inhibits the invasion and migration of hepatocellular carcinoma cells by targeting the ubiquitination and degradation of Metastasis-Associated 1 (MTA1) protein." (PMID 41315221, 2025). "The metastatic tumor antigen 1 (MTA1) protein is associated with tumor invasiveness and poor prognosis in patients with hepatocellular carcinoma (HCC), particularly in those with hepatitis B virus (HBV)-related HCC." (PMID 27323415, 2016). "Only one report demonstrated that MTA1 overexpression was associated with larger tumor size in hepatocellular cancer." (PMID 23941622, 2013). "In NSCLC, hepatocellular carcinoma (HCC), and osteosarcoma (OS), the regulatory networks of metastasis-associated gene 1 (MTA1) and miR-183 were extremely significant." (PMID 37174715, 2023). "In hepatocellular carcinoma (HCC), metastasis-associated 1 (MTA-1), which is involved in metastatic progression, was shown to be a substrate of Efp." (PMID 35954308, 2022). "Tet inhibits Wnt/β-catenin pathway activity and reduces metastatic tumor antigen 1 (MTA1) expression, preventing metastasis in human hepatocellular carcinoma (HCC)." (PMID 36052124, 2022). "Some studies suggest that TRIM25 is an E3 ligase that interacts with and degrades MTA-1 protein, which is one of the important mediators of metastatic progression in hepatocellular carcinoma." (PMID 36360326, 2022). "For instance, pterostilbene suppressed the growth and invasion of hepatocellular carcinoma through effectively inhibiting the levels of the MTA1/HDAC1/NuRD complex and promoting phosphatase and tensin homolog (PTEN) acetylation." (PMID 34924813, 2021). "Pterostilbene suppressed the growth and invasion of hepatocellular carcinoma through inhibiting the MTA1/HDAC1/NuRD complex and promoting PTEN acetylation." (PMID 34924813, 2021). "However, a study of liver cancer cell lines (HuH6, SNU449, and THLE-2 cells) and normal cell lines has found that metastasis-associated 1 protein (MTA1) reduces the phosphorylation of H1.2 at T146 by proteasomal degradation of DNA-PK, which in turn promotes hepatocellular carcinoma (HCC)." (PMID 36674981, 2023). "MTA1 gene expression correlates with cancer progression and degree of invasion for hepatocellular carcinoma (HCC) and other carcinomas." (PMID 26503703, 2015). "In hepatocellular carcinoma, Pterostilbene decreased MTA1 expression and HDAC1 activity, disrupting the MTA1/histone deacetylase complex and leading to restored PTEN acetylation and subsequent induction of apoptosis in cancer cells." (PMID 38155902, 2023). "Using affinity purification and mass spectrometry assays to identify SMYD3-associated proteins in hepatocellular carcinoma (HCC) cells, we found several previously undiscovered SMYD3-interacting proteins, including the NuRD (MTA1/2) complex, the METTL family, and the CRL4B complex." (PMID 36575438, 2022). "Knockdown of MTA1 or MTA2 had the same effect as knockdown of SMYD3 on proliferation and invasion of hepatocellular carcinoma cells." (PMID 36575438, 2022). "In order to further elucidate mechanism of interaction between MTA1 and HIF-1α, hepatocellular carcinoma cell line HepG2 was employed." (PMID 28589145, 2017). "Hepatocellular carcinoma cell line HepG2, tube formation assay, and CAM assay were also applied to explore the preliminary mechanism of MTA1 in angiogenesis." (PMID 28589145, 2017). "Hepatocellular carcinoma cell line HepG2, tube formation assay, and chorioallantoic membrane (CAM) assay were applied to explore the mechanism of MTA1 in angiogenesis." (PMID 28589145, 2017).
hepatocellular carcinoma (continued). "HuR targets include invasive and metastatic RNAs (e.g., MMP-9, MTA1, and uPA), angiogenic RNAs (e.g., VEGF-1 and HIF-1), and cell proliferative RNAs (e.g., EGF, cyclin A, cyclin B1, cyclin E, and cyclin D1), through which it can influence hepatocellular carcinoma progression." (PMID 37540723, 2023).
colorectal cancer (14 papers, 2015 to 2025). A primary or metastatic malignant neoplasm that affects the colon or rectum. "FTO is a m6A demethylase that promotes breast tumor progression by inhibiting BNIP3, whereas another study reported inhibitory effect of FTO on metastasis by targeting demethylating metastasis-associated protein 1 (MTA1) mRNA in colorectal cancer." (PMID 35090515, 2022). "It has been confirmed that metastasis associated protein 1 (MTA1) is a downstream target of miR-543 in colorectal cancer." (PMID 32410569, 2020). "eIF5A2, in turn, was demonstrated to regulate MTA1 (metastasis-associated 1) via c-Myc in gastric cancer and colorectal carcinoma." (PMID 27433286, 2016). "Furthermore, FTO functioned as a tumor suppressor in colorectal cancer by inhibiting metastasis-associated protein 1 (MTA1) expression in an m6A-dependent manner." (PMID 35217651, 2022). "In our study, we elucidated the regulatory effect of MTA1 on tumor-associated macrophages (TAMs) and how this regulation affects the antitumor effect of cytotoxic T lymphocytes (CTLs) in the tumor microenvironment of colorectal cancer." (PMID 35350571, 2022). "ZBTB48 ablation also accelerates growth of HCT-116 colorectal cancer cells and modulates FTO-dependent regulation of Metastasis-associated protein 1 (MTA1) transcripts by controlling the binding to MTA1 mRNA of the m6A reader IGF2BP2." (PMID 39300486, 2024). "For example, the upregulated miR-421 expression has been shown to inhibit the proliferation and metastasis of colorectal cancer by targeting MTA1." (PMID 36829221, 2023). "Next, we performed a T cell cytotoxicity assay to further investigate the effect of MTA1 expression in colorectal cancer cells on T cell cytotoxicity in the tumor microenvironment." (PMID 35350571, 2022). "In our study, we also emphasized that the relatively decreased macrophages impaired the antitumor effect in MTA1-overexpressing colorectal cancer." (PMID 35350571, 2022). "MTA1 upregulation in colorectal cancer was found to drive an immunosuppressive tumor microenvironment." (PMID 35350571, 2022). "MTA1 is generally overexpressed in tumors, and also in colorectal cancer, and the MTA1 expression level is negatively correlated with the overall survival of the patients in the colorectal cancer cohort." (PMID 35350571, 2022). "The downregulation of CCL2 in MTA1-overexpressing colorectal cancer impaired the recruitment of monocytes and finally formed macrophages with a relatively decreased tumor microenvironment." (PMID 35350571, 2022). "Macrophages cocultured with MTA1-overexpressing colorectal cancer cells significantly upregulated the M2-like macrophage markers Arg-1, CD206 and Ym1 but significantly downregulated the expression of the immunostimulator IL-6." (PMID 35350571, 2022). "For instance, MTA1, as a direct target of miR-421, was previously illustrated to manipulate the cell progression of colorectal cancer." (PMID 35764613, 2022). "Here, we report the ability of MTA1 to rewire the transcriptome and proteome of colorectal cancer cells, resulting in an immunosuppressive microenvironment." (PMID 35350571, 2022). "Then, we analyzed the function of macrophages modulated by MTA1-overexpressing colorectal cancer cells." (PMID 35350571, 2022). "In summary, the high expression of MTA1 in colorectal cancer decreased the interaction between tumor cells and T cells, which can be rescued by the presence of classical macrophages." (PMID 35350571, 2022). "Despite the lack of research regarding the role of MTA1 in experimental colitis, a number of studies have documented the involvement of MTA1 in colorectal cancer and inflammatory responses." (PMID 35764613, 2022). "In the tumor microenvironment of MTA1-upregulated colorectal cancer, although CD8+ T cells were significantly enriched, macrophages were significantly decreased, which impaired the CTL effect of the CD8+ T cells on tumor cells." (PMID 35350571, 2022).
colorectal cancer (continued). "The results showed that colorectal cancer patients with high levels of MTA1 expression tended to be enriched with lower immunomodulation enrichment scores, which reflects an immunosuppressive status in their tumor tissues." (PMID 35350571, 2022). "In total, MTA1-overexpressing colorectal cancer cells significantly induced polarization of macrophages into M2 tumor-associated macrophage (TAM) phenotypes." (PMID 35350571, 2022). "The results from flow cytometry showed that higher MTA1 expression in CT26 colorectal cancer cells promoted the secretion of Ifng in T cells, reflecting T cell activation." (PMID 35350571, 2022). "What’s more, existing evidence further suggests that MTA1 plays a regulatory role in the proliferation and metastasis of colorectal cancer cells." (PMID 35764613, 2022). "It has been reported that miR-543 was negatively correlated with the expression of MTA1 in clinical samples of colorectal cancer and the direct interaction between miR-543 and MTA1 was confirmed by double luciferase experiment at the molecular level." (PMID 32410569, 2020). "Thus, we found that in MTA1-upregulated colorectal cancer, immune factors were generally downregulated." (PMID 35350571, 2022). "We then analyzed the correlation between the levels of chemokines and MTA1 in colorectal cancer cell lines in the Cancer Cell Line Encyclopedia (CCLE) database, and there was a significant negative correlation between the levels of MTA1 and the panel of chemokines." (PMID 35350571, 2022). "Among the results derived from various immune infiltration evaluation algorithms, the expression level of MTA1 in colorectal cancer was significantly positively correlated with the level of CD8+ T cell infiltration and negatively correlated with macrophage infiltration." (PMID 35350571, 2022). "Most of the chemokines were downregulated with MTA1 overexpression in colorectal cancer cell lines." (PMID 35350571, 2022). "In the results of phenotype analysis by flow cytometry, colorectal cancer cells expressing higher MTA1 promoted the polarization of macrophages to the CD206+ phenotype while inhibiting CD163+ polarization without affecting the polarization of the CD86+ phenotype." (PMID 35350571, 2022). "Based on the clue that MTA1 has been associated with inflammation in colorectal cancer, we primarily tried to explore how overexpressed MTA1 influences the immune infiltration states and immune response in the tumor microenvironment of a TCGA colorectal cancer cohort." (PMID 35350571, 2022). "Colorectal cancer cells expressing high levels of MTA1 tend to induce M2-like macrophages." (PMID 35350571, 2022). "Gene set enrichment analysis of the top 500 MTA1 coexpression genes analyzed by the cluster profiler revealed immune biological processes at the top of the list, suggesting that MTA1 may be immune signature-related in colorectal cancer." (PMID 35350571, 2022). "In colorectal cancer, the overexpression of EIF5A2 has been reported to promote cancer aggressiveness by upregulating MTA1 to induce EMT." (PMID 32605067, 2020). "To explore the influence of MTA1 expression in tumor cells on the polarization of macrophages in the tumor microenvironment, we separately cocultured MTA1-knockdown, MTA1-overexpressing and control CT26 mouse colorectal cancer cells with mouse macrophages." (PMID 35350571, 2022). "Additionally, IGF2BP2 decreases MTA1 expression in the absence of FTO, indicating that FTO and IGF2BP2 control MTA1 expression in colorectal cancer via methylation." (PMID 40919129, 2025).
lung carcinoma (13 papers, 2013 to 2025). "In lung cancer, EpCAM has been found to be a downstream target of metastasis-associated protein 1 (MTA1), and MTA1 overexpression can increase EpCAM levels and enhance tumor metastasis, leading to poor prognosis." (PMID 35719973, 2022). "The same authors also pointed out that the possible signaling pathway HPV16/miR-30c-2*/MTA-1 might offer a new therapeutic target for patients with HPV-associated lung cancer." (PMID 30563114, 2018). "The prognostic role of MTA1 expression in lung cancer remained controversial, we performed this meta-analysis to assess the prognostic value of MTA1 expression in lung cancer." (PMID 29061215, 2017). "The pooled hazard ratio (HR) were used to assess the relationship between MTA1 expression and prognosis of lung cancer." (PMID 29061215, 2017). "MTA1 was shown to have markedly nuclear positivity in some cancerous tissue, such as lung cancer, gastric, colorectal and ovarian cancer." (PMID 26878004, 2016). "In this context, overexpression of MTA1 in the three lung cancer cell lines increased EpCAM expression at protein level." (PMID 26698569, 2015). "What’s more, both MTA1 and EpCAM, correlated to each other, were overexpressed in lung cancer tissues and significantly correlated with their clinical stages, tumor diameters, lymph node metastasis." (PMID 26698569, 2015). "Despite some targets that have been documented, mechanistic understanding that how MTA1 induces metastasis is still opaque in lung cancer." (PMID 26698569, 2015). "Of the 118 early stage lung cancer specimens, a high level of MTA1 was detected in 65 (55.10 %) cancer tissues, but only in 2 (16.70 %) of 12 non-neoplastic lung tissues." (PMID 26698569, 2015). "In this study, we demonstrated that over-expression of MTA1 induced EpCAM expression in human lung cancer cell lines, leading to increased cell invasion and migration." (PMID 26698569, 2015). "The results presented here proved that MTA1 upregulated EpCAM in cancers for the first time, and MTA1 overexpression promoted lung cancer invasiveness in vitro." (PMID 26698569, 2015). "MTA1 upregulated EpCAM expression in lung cancer cell lines, and EpCAM overexpression rescued the inhibitory effects by silencing MTA1 on cell invasion and migration in vitro." (PMID 26698569, 2015). "The staining of MTA1 protein exhibited both nuclear and cytoplasmic location in the lung cancer tissues." (PMID 26698569, 2015). "In summary, our results provided a new insight into MTA1-mediated invasion and migration by enhancing EpCAM level in lung cancer." (PMID 26698569, 2015). "And MTA1 and EpCAM overexpression independently predicted unfavorable prognosis in our 118 lung cancer patients." (PMID 26698569, 2015). "In our study, we also demonstrated that MTA1 protein was significantly higher in lung cancer tissues (including small cell lung cancer) than in normal lung tissues." (PMID 26698569, 2015). "Taken together, these results indicate that MTA1 signals through EpCAM, at least in part, to stimulate the invasion and migration abilities in lung cancer cells." (PMID 26698569, 2015). "Expression of MTA1 and EpCAM is strongly correlated to each other in lung cancer tissues and high-level MTA1 and EpCAM predict patients’ poor prognosis in multivariate analysis." (PMID 26698569, 2015). "Multivariate analysis indicated that local advancement (p = 0.03), MTA1 overexpression (p = 0.001) and EpCAM overexpression (p = 0.045) of the lung cancer tissues remained significant in predicting unfavorable overall survival." (PMID 26698569, 2015). "Further studies are needed to elucidate the mechanism by which MTA1 downregulates the transcription of miR-125b in lung cancer cells." (PMID 23718732, 2013). "In summary, we found that the expression of MTA1 and miR-125b is negatively correlated in lung cancer cells and they have antagonistic effects on the migration and invasion of NSCLC cells." (PMID 23718732, 2013).